IGLL5 (immunoglobulin lambda like polypeptide 5)
Diseases named in the same sentence as IGLL5 in open-access papers:
IGLL5 is named in the same sentence as 37 diseases in open-access papers, as found by Europe PMC text mining. Sharing a sentence is not in itself a finding about the gene and the disease. The quoted sentences say what the papers report.
lymphoma (13 papers, 2017 to 2026). A malignant (clonal) proliferation of B- lymphocytes or T- lymphocytes which involves the lymph nodes, bone marrow and/or extranodal sites. "IGLL5, which has been described as frequently mutated in other lymphomas, was identified as significantly downregulated in ZNF217 altered specimens." (PMID 37648814, 2023). "Only a limited number of research has shown that IGLL5 has a frequent mutation in chronic lymphocytic leukemia, lymphoma, and multiple myeloma; besides, IGLL5 has a prognostic value in several diseases, such as multiple myeloma and glioblastoma." (PMID 33449444, 2021). "Five genes, all with variants in two cases, were shown to be associated with lymphoma pathogenesis (ID3, PAX5, TBL1XR1, IGLL5 and APC) in previous studies." (PMID 35205758, 2022). "BCL7A, IGLL5, and BCL2 are likely false positives as they were mutated primarily in lymphomas, where they are known targets of local AID-mediated somatic hypermutation." (PMID 36396655, 2022). "Notable genes with SNV-associated increased expression include TERT, COPS3, POLE2 and HDAC2—involving multiple cancer types—MYC, BCL2, PIM1 and IGLL5—involving lymphomas—and CYHR1—involving pediatric low-grade gliomas." (PMID 33554123, 2021). "For example, several of our top genes showed a tight SNV clustering pattern associated with elevated expression, including MYC, BCL2, PIM1 and IGLL5 in lymphoma." (PMID 33554123, 2021). "IGLL5 expression in MM cell lines within the CCLE is second only to Burkitt’s Lymphoma cell lines; more generally, and as with DERL3, IGLL5 expression is higher in B-cell malignancies than in other cancer types." (PMID 29563506, 2018).
multiple myeloma (8 papers, 2018 to 2024). "Taken together, the analysis of the MIF and CLEC signaling pathways reinforced the importance of the C0 IGLL5+ Myeloma Cells subgroup and its association with the MIF pathway, as well as the relevance of the CLEC pathway to T_NK cells." (PMID 39281682, 2024). "Fusion or mutation of IGLL5 was identified in Burkitt lymphoma, multiple lymphadenopathy, diffuse large B cell lymphoma, multiple myeloma, and chronic lymphocytic leukemia." (PMID 34888353, 2021). "Notably, an independent analysis revealed that IGLL5 mutation serves as a contributing factor to the heightened risk of early progressive disease in multiple myeloma patients." (PMID 39281682, 2024). "Notably, the MIF (Macrophage Migration Inhibitory Factor) signal pathway was found to be associated with the C0 IGLL5+ Myeloma Cells subgroup, indicating its importance in the signaling network of this subgroup." (PMID 39281682, 2024). "It has been reported that IGLL5 may act as a risk factor and was related with metastasis and poor prognosis of multiple myeloma." (PMID 34888353, 2021). "The four identified cell subgroups were as follows: C0 IGLL5+ Myeloma Cells (724 cells), C1 IGHG4+ Myeloma Cells (310 cells), C2 MALAT1+ Myeloma Cells (305 cells), and C3 IGHG1+ Myeloma Cells (149 cells)." (PMID 39281682, 2024). "Among them, the biological processes with the highest correlation with C0 IGLL5+ Myeloma Cells were endoplasmic and reticulum." (PMID 39281682, 2024). "The results indicated that the C0 IGLL5+ Myeloma Cells subgroup had the largest number and the highest centrality score within the MIF signaling pathway." (PMID 39281682, 2024). "The researchers recognized this constraint and emphasized the importance of further studies to confirm the involvement of IGLL5+ Myeloma Cells in multiple myeloma." (PMID 39281682, 2024). "Four subsets were visualized through box plot, UMAP plot, and facet plots, revealing that C0 IGLL5+ Myeloma Cells’ expression on the MMP and TIMP pathways." (PMID 39281682, 2024). "Previous researches had shown a strong connection between this particular subset and the advancement of multiple myeloma, underscoring the importance of IGLL5 in the progression of the disease." (PMID 39281682, 2024). "We discovered three distinct incoming signal patterns: Pattern 1 (involving T_NK cells and pDCs), Pattern 2 (involving C0 IGLL5+ Myeloma Cells), and Pattern 3 (involving C3 IGHG1+ Myeloma Cells)." (PMID 39281682, 2024). "This analysis resulted in the identification of four distinct cell subsets: C0 IGLL5+ Myeloma Cells, C1 IGHG4+ Myeloma Cells, C2 MALAT1+ Myeloma Cells, and C3 IGHG1+ Myeloma Cells." (PMID 39281682, 2024). "In particular, our study shed new insights into the coordinated interactions involving the C0 IGLL5+ Myeloma Cells subgroup and various other cell types." (PMID 39281682, 2024). "Through these analyses, we identified the specific subgroup of myeloma cells that became the focus of our study, namely the C0 IGLL5+ Myeloma Cells subgroup." (PMID 39281682, 2024). "By utilizing the CellChat communication pattern analysis, we were able to uncover the coordinated interactions between the C0 IGLL5+ Myeloma Cells subgroup and other cell types." (PMID 39281682, 2024). "The analysis of the MIF and CLEC signaling pathways reinforced the relevance of the C0 IGLL5+ Myeloma Cells subgroup and provided insights into cell-cell interactions and immune regulation in multiple myeloma." (PMID 39281682, 2024). "The findings from the analysis of the MIF signaling pathway further supported the strong correlation between the C0 IGLL5+ Myeloma Cells subgroup and this pathway." (PMID 39281682, 2024). "Prior research had offered important information on the importance of the gene known as IGLL5 in relation to multiple myeloma." (PMID 39281682, 2024).
multiple myeloma (continued). "IGLL5 was also demonstrated to be frequently mutated in B-cell malignancies, such as Hodgkin’s lymphoma, diffuse large B-cell lymphoma (DLBCL), multiple myeloma (MM), and CLL with translocations involving IGH." (PMID 36874132, 2023). "Notably, we observed that C0 IGLL5+ Myeloma cells were only present in two patients within the multiple myeloma (MM) group." (PMID 39281682, 2024). "Notably, the myeloma cell subgroup C0 IGLL5+ Myeloma Cells exhibited high expression of genes related to the MIF pathway." (PMID 39281682, 2024). "Moreover, previous studies had reported that MM cells express high levels of MIF, which aligned with the current findings and reinforces the significance of the C0 IGLL5+ Myeloma Cells subgroup in this study." (PMID 39281682, 2024). "Notably, the C0 IGLL5+ Myeloma cells were found to be positioned towards the end of the pseudotime series." (PMID 39281682, 2024). "Interestingly, we observed that MIF played a significant role in both incoming and outgoing signaling of C0 IGLL5+ Myeloma cells." (PMID 39281682, 2024). "Therefore, through multiple experiments, it was found that IGLL5 knockdown can reduce the migration, invasion, and proliferation abilities of multiple myeloma cells." (PMID 39281682, 2024). "Additionally, we observed three outgoing signal patterns: Pattern 1 (involving C0 IGLL5+ Myeloma Cells), Pattern 2 (involving C3 IGHG1+ Myeloma Cells), and Pattern 3 (involving T_NK cells, B cells, and pDCs)." (PMID 39281682, 2024). "Additionally, the most activated TFs in each subgroup within the M1-M5 modules were identified as follows: MAF in the C0 IGLL5+ Myeloma Cells subgroup, LEF1 in the C1 IGHG4+ Myeloma Cells subgroup, TCF12 in the C2 MALAT1+ Myeloma Cells subgroup, and CREB5 in the C3 IGHG1+ Myeloma Cells subgroup." (PMID 39281682, 2024).
breast carcinoma (7 papers, 2015 to 2023). "Is of note that in lymph nodes breast cancer patients, IGLL5 is frequently fused with variants of IGLV1 that is located ∼ 500 kb upstream of IGLL5." (PMID 28185911, 2017). "For fusion genes, the most frequently seen in the NSLN positive group was IGLL5, which was identified as one of the best predictors for relapse-free survival with >85 % accuracy in breast cancer patients." (PMID 26311227, 2015). "The fusion of IGLL5 was suggested to promote metastasis of the lymph nodes and play a role in breast cancer development, though its role in MΦs in the TME of CC remains unclear." (PMID 36683048, 2023). "IGLL5 is also correlated with glioblastoma survival and breast cancer, which could serve as a biomarker for relapse-free survival in breast cancer with more than 85% accuracy." (PMID 34888353, 2021).
chronic lymphocytic leukemia (6 papers, 2018 to 2024). "Although IGLL5 was reported to be recurrently mutated in chronic lymphocytic leukemia (CLL) and diffuse large B-cell lymphoma (DLBCL), none of these SNV were overlapped." (PMID 35359413, 2022).
Burkitt lymphoma (4 papers, 2018 to 2023). A rare form of malignant mature B-cell non-Hodgkin lymphoma. "Several studies have supported the adverse effect of mutated IGLL5, such as the pathogenesis of MM and Burkitt lymphoma, IGH translocations in CLL, and association with R/R DLBCL." (PMID 36874132, 2023). "In addition, variants were detected in ID3 and IGLL5, two genes recurrently mutated in Burkitt lymphoma." (PMID 35205758, 2022).
B cell lymphoma (3 papers, 2020 to 2025). "Another study showed that IGLL5 is one of the frequently mutated genes in mature B cell lymphomas." (PMID 40566633, 2025).
COVID-19 (3 papers, 2021 to 2025). A disease caused by infection with severe acute respiratory syndrome coronavirus 2. "On the other hand, the high expression of IGLL5 7 days after infection with COVID-19 may be the result of an adaptive immune response, suggesting that this characteristic gene has a potential role in antibody production and immune memory cell formation." (PMID 40566633, 2025). "The levels of immunity-related proteins (IGHG1, IGLL5, and IGKV4-1) were slightly decreased in the acute phase of COVID-19, confirming that immunity had been suppressed." (PMID 38965561, 2024).
clear cell renal cell carcinoma (2 papers, 2021 to 2025). "In summary, IGLL5 may have potential as a novel prognostic biomarker of clear cell renal cell carcinoma." (PMID 33449444, 2021).
follicular lymphoma (2 papers, 2021). Follicular lymphoma is a form of non-Hodgkin lymphoma characterized by a proliferation of B cells whose nodular structure of follicular architecture is preserved. "Of these, mutations in CREBBP, KMT2D, TNFRSF14 and RRAGC were enriched in follicular lymphoma, and those of BTG2, HLA-A, PIM1, IGLL5, SOCS1, CD83 and SGK1 were enriched in DLBCL." (PMID 33945543, 2021).
Hodgkins lymphoma (2 papers, 2021 to 2023). A heterogeneous group of malignant lymphoid neoplasms of B-cell origin characterized histologically by the presence of Hodgkin and Reed-Sternberg (HRS) cells in the vast majority of cases. "CD79 has been extensively studied in hematological tumors and has been reported to be more positive in elderly Hodgkin’s lymphoma patients with poor prognosis; however, IGLL5 and LHFPL2 are less often studied in tumors and their functions remain unknown." (PMID 34900411, 2021).
Primary immunodeficiency (2 papers, 2021 to 2022). "In addition, results of the KEGG enrichment analysis demonstrated that IGLL5 was associated with primary immunodeficiency and chemokine signaling pathways." (PMID 34753383, 2021).
prostate carcinoma (2 papers, 2021 to 2025). A carcinoma that arises from epithelial cells of the prostate gland. "IGLL5, the main positive contributor to both nodules “A” and “B”, was correlated with tumor-infiltrating immune cells in kidney cancer, suggesting an interesting study to determine whether it plays a similar role in prostate cancer." (PMID 34209090, 2021).
renal cell carcinoma (2 papers, 2021 to 2025). "A specific enrichment analysis of immune cells related to IGLL5 and IL2RA was also conducted in two types of renal cell cancer." (PMID 34888353, 2021).
-plasmacytic lymphomas (1 paper, 2019). "IGLL5 mutations have also been reported in other marginal zone (nodal and extranodal) and lympho-plasmacytic lymphomas." (PMID 31320741, 2019).
chronic periodontitis (1 paper, 2018). A chronic inflammatory process that affects the tissues that surround and support the teeth. "The levels of the four most highly up-regulated genes, IGLL5, SSR4, MZB1 and XBP1, were investigated in gingival RNA samples from ten subjects (six with periodontitis and four healthy controls)." (PMID 29921943, 2018).
Crohn disease (1 paper, 2024). A gastrointestinal disorder characterized by chronic inflammation involving all layers of the intestinal wall, noncaseating granulomas affecting the intestinal wall and regional lymph nodes, and transmural fibrosis. "For instance, three markers JCHAIN/IgJ, IGLL5 and MZB1, which are strong markers for B-cells, are also markers of plasmacytoid cells in Crohn's Disease mesenteric adipose fat." (PMID 38978787, 2024).
cutaneous melanoma (1 paper, 2022). A primary melanoma arising from atypical melanocytes in the skin. "After correcting for multiple testing, the only significant promoters were TERT in cutaneous melanoma and pan-cancer; BCL7A, IGLL5, BCL2, and POLR3E pan-cancer; and HNRNPR in uterine adenocarcinoma." (PMID 36396655, 2022).
depression (1 paper, 2022). "In addition, there are few studies on IL7R, IGLL5, and CD79A in depression." (PMID 36561317, 2022).
papillary renal cell carcinoma (1 paper, 2023). A rare subtype of renal cell carcinoma, arising from the renal tubular epithelium and showing a papillary growth pattern, which typically manifests with hematuria, flank pain, palpable abdominal mass or nonspecific symptoms, such as fatigue, weight loss or fever. "Although TME existed heterogeneity, one study identified the core immune-related genes (IGLL5 and IL2RA) in ccRCC and papillary renal cell carcinoma." (PMID 37108666, 2023).
renal carcinoma (1 paper, 2023). A carcinoma arising from the epithelium of the renal parenchyma or the renal pelvis. "The biological function of the Immunoglobulin Lambda-Like polypeptide 5 (IGLL5) is yet to be described comprehensively but IGLL5 levels were recently found to be positively correlated with tumor-infiltrating immune cells in renal cancer." (PMID 37435088, 2023).
Sepsis (1 paper, 2025). Sepsis is defined as life-threatening organ dysfunction caused by a dysregulated host response to infection. "A PPI network identified key hub genes, including IGLL5, BCL2L1, TNFSF10, and SNCA, with significant connections, highlighting their critical roles in sepsis development and potential as biomarkers or therapeutic targets." (PMID 40362669, 2025).
tumor (21 papers, 2012 to 2025). "The IGLL5 gene encodes one of the immunoglobulin lambda-like polypeptides that is involved in tumor progression." (PMID 36561317, 2022). "IGLL5 encodes one of the immunoglobulin lambda‐like polypeptides and plays a significant role in tumor progression." (PMID 32012488, 2020). "In addition, the gene fusions between the immunoglobulin lambda variables and IGLL5 were detected in the filtering result of TopHat-Fusion, which might represent immune rearrangements in tumor-associated B cells." (PMID 22905095, 2012). "Of these, five were present in at least one tumor from each cohort: IGLL5 p.L28M, MTMR1 p.R389Q, MYD88 p.S206C, PABPC3 p.K231E." (PMID 40634688, 2025). "Immunoinfiltration analyses revealed that three types of tumor‐infiltrating immune cell were positively correlated with IGLL5 expression." (PMID 33449444, 2021). "Frequent loss-of-function mutations were also observed for CD58, IGLL5, IRF1, LTB, MGA and VMP1 in blood cancers, implicating a potential tumour-suppressive role of these genes in the pathogenesis in this tissue type." (PMID 33420369, 2021). "Differential expression analysis of IGLL5 between normal samples and ccRCC samples showed that IGLL5 expression was higher in tumor samples (P < 0.001)." (PMID 33449444, 2021). "In lymphoid tissues far away from tumor cell areas expression of the immune-related gene CD74 was observed while in tissues in close proximity to tumor cell areas, expression of the immune-related gene IGLL5 was seen." (PMID 35008286, 2021). "IGLL5 and IL2RA expression were also positively associated with the stage of ccRCC patients, including high tumor stage, tumor grade, T stage, and more lymph node metastases (p < 0.05)." (PMID 34888353, 2021). "Moreover, the expression of IGLL5 was correlated with three types of tumor-infiltrating immune cells (TICs): naive B cells, plasma cells, and activated CD4 memory T cells." (PMID 40566633, 2025). "However, some studies have also demonstrated that the overexpression of IGLL5 affects immunological parameters, generating a more immune-suppressed tumor microenvironment." (PMID 36874132, 2023). "For ccRCC, IHC images indicated that normal renal tissue had weak staining for IGLL5 and IL2RA, but relatively strong staining patterns for IGLL5 and IL2RA were observed in the cytoplasm of tumor tissues." (PMID 34888353, 2021). "In addition, they noted that PMEL and SPP1 were overexpressed in the tumor cell cluster whereas lymphoid tissue regions far away from and near, the tumor cell areas were characterized by expression of the immune-related genes CD74 and IGLL5, respectively." (PMID 35590346, 2022). "The results suggested that IGLL5 had a correlation with the occurrence and development of tumor, and the UR expression of IGLL5 indicated negative prognosis of ccRCC." (PMID 33449444, 2021). "We hypothesized that CXCL13 expressed in T cells and CD79A and IGLL5 expressed in B cells could affect the expression of LHFPL2 gene through the CD45 signaling pathway, acting on macrophages, thus jointly playing a role in tumor regulation." (PMID 34900411, 2021).
cancer (7 papers, 2015 to 2026). A tumor composed of atypical neoplastic, often pleomorphic cells that invade other tissues. "Indeed, we found that several cancer-related genes were recurrently hit by somatic variants in multiple non-cancer blood samples, including three previously reported CHIP genes: IGLL5, RAD21, and IDH2." (PMID 41505106, 2026). "All these genes have already been associated with hypermutated regions in BCLs (BCL2, BCL6, BCL7A, BIRC3, CIITA and ST6GAL1) or listed in the Cancer Gene Census (BCL2, BCL6, BCL7A, BIRC3, CIITA, IGLL5 – in the IGL@ locus – and LPP)." (PMID 25903198, 2015).
infection (3 papers, 2023 to 2025). The state of being infected such as from the introduction of a foreign agent such as serum, vaccine, antigenic substance or organism. "Controls were established with a negative control group and an infection group with IGLL5 knockdown." (PMID 39281682, 2024).
IGLL5 also shares sentences with these, for which no sentence is quoted: diffuse large B-cell lymphoma (3 papers); autoimmune disease (2); blood cancer (2); glioblastoma (2); liver cancer (2); glioma (1); hairy cell leukemia (1); kidney cancer (1); lymphoid neoplasm (1); lymphoproliferative disorders (1); monoclonal gammopathy of undetermined significance (1); POEMS syndrome (1); type 1 diabetes (1).